APOE (apolipoprotein E)
Diseases named in the same sentence as APOE in open-access papers (continued):
Sharing a sentence is not in itself a finding about the gene and the disease.
dementia (continued). "Multivariable logistic regression and Mendelian randomization results were similar when we further adjusted for dementia genetic variables (APOE-ε4 allele carrier status and general cognition PGS)." (PMID 34248819, 2021). "Previous studies have suggested that the APOE ɛ4 allele plays a role in the risk and age at onset of dementia in DS; however, data on in vivo biomarkers remain scarce." (PMID 34228042, 2021). "The APOE gene consists of three different alleles, ε2, ε3, and ε4, with ε4 being associated with dementia and cardiovascular diseases." (PMID 34828374, 2021). "We studied if the AD‐PRSs, the APOE genotype, and the interaction of these, predicted risk of dementia by analyzing the full age spectrum, as well as subgroups aged 70 to 94 years and 95 years or older." (PMID 33532541, 2021). "A reduced risk of decline was observed in dementia-related domains of everyday skills, memory and orientation, and personality and behaviour while adjusting for the effect of age, sex, ID level, APOE genotype, and CVD." (PMID 33925348, 2021). "In APOE ɛ4 carriers the 39‐SNPs AD‐PRS was instead related to a reduced risk of dementia (HR 0.62; 95% CI 0.41–0.95, P = .03)." (PMID 33532541, 2021). "APOE ɛ4 carriership only predicted dementia in the low‐risk tertile of the AD‐PRSs (39‐SNPs AD‐PRS: HR 1.72; 95% CI 1.01–2.92, P = .05, 1e–5 AD‐PRS: HR 3.66; 95% CI 1.99–6.73, P = 3 × 10–5)." (PMID 33532541, 2021). "Our study indicated that APOE-ε4 genotype was the strongest risk for dementia in the model adjusting for genetic predisposition and smoking." (PMID 34155245, 2021). "Previous studies have shown that the effect of the APOE gene on the risk of cognitive decline and dementia was modified by other genetic factors, including ABCA7, SORL1, PICALM, CR1, BIN1, and TREM2, showing complex gene-gene interactions." (PMID 34214049, 2021). "We studied cumulative incidence of dementia and cognitive decline, stratified by APOE genotypes and polygenic risk score (PRS) tertiles, in 12,978 participants of the ASPirin in Reducing Events in the Elderly (ASPREE) trial." (PMID 34041846, 2021). "Many studies suggest that cognitive reserve produces different effects according to APOE genotype, mainly demonstrating that the protective effects of cognitive reserve against dementia are stronger in healthy subjects with the ε4 allele." (PMID 34366926, 2021). "In those aged ≥95 years, 1e–5 AD‐PRS was associated with incident dementia (HR 1.15, 95% CI 1.01–1.32, P = .04), while the 39‐SNPs AD‐PRS was associated with incident dementia among APOE ɛ4 non‐carriers only (HR 1.28; 95% CI 1.10–1.50, P = 2 × 10–3)." (PMID 33532541, 2021). "The FI-dementia association remained significant after further adjustment for APOE ɛ4 carrier status and when considering the competing risk of death." (PMID 34657626, 2021). "Incidence of dementia among healthy older individuals is low across all genotypes; however, APOE ε4 and high PRS increase relative risk." (PMID 34041846, 2021). "APOE ε4 heterozygosity/homozygosity was associated with a 2.5/6.3‐fold increased dementia risk and 1.4/1.8‐fold cognitive decline risk, versus ε3/ε3 (p < 0.001 for both)." (PMID 34041846, 2021). "The present study compared three important pathological risk factors for dementia among cognitively normal elderly in Japan and in the US, who were matched for age, sex, and APOE genotype." (PMID 34573201, 2021). "Here, we found that APOE ε4 carriers also have an increased risk for dementia (z‐value = 11.05, OR 3.15 [2.5% 2.53 to 97.5% 3.92], P < .0001)." (PMID 33969178, 2021). "We first compared ENHO expression between brain structures and between individuals based on dementia state and APOE allele." (PMID 34462439, 2021). "Carriers of two ε4 alleles (APOE ε4ε4 genotype) had the greatest risk of developing dementia after adjusting for potential confounders." (PMID 34155245, 2021).
dementia (continued). "Strikingly, numerous dementia-associated genes (i.e., APOE, ABCA1, ABCA7, CLU, PLCγ2, TREM2) are critical to lipid homeostasis and selectively expressed in microglia." (PMID 33841127, 2021). "We found accelerated functional aging in persons with symptomatic sAD (MCI or dementia) when compared with others who were asymptomatic, but at increased risk of sAD (APOE ε4 participants from our test set)." (PMID 34504080, 2021). "The 310 participants who developed dementia were older, were more often women, had a lower education level, had poorer cognitive performance, and were more likely to carry at least one APOE ε4 allele (46% vs 27%, p < 0.001)." (PMID 33397450, 2021). "APOE ɛ4 carriership was associated with increased risk of dementia, especially in the low‐ and middle‐risk tertiles of the AD‐PRSs, while ɛ2 carriership was associated with reduced risk." (PMID 33532541, 2021). "This points to an independence of allelic and methylation variation of APOE for the risk to develop dementia." (PMID 34831288, 2021). "We did not investigate several well-known risk factors for dementia, including the apolipoprotein E gene and education level, or the effects of antidepressants or other depression treatments on the risk of dementia." (PMID 34260630, 2021). "Individually, these common genetic variants have low effect sizes, yet when combined into a PRS can enable risk‐stratification for dementia indications beyond APOE genotype." (PMID 34041846, 2021). "In those aged ≥95 years, the results were similar for the AD‐PRSs, while APOE ɛ4 only predicted dementia in the low‐risk tertile of AD‐PRSs." (PMID 33532541, 2021). "Further, in a recent meta‐analysis of three population‐based cohorts of cognitively normal subjects aged 60–75 years (total N = 11,771), the risk of dementia in APOE ε4/ε4 homozygotes (N = 134) to age 70–75 years was 11.2%." (PMID 34041846, 2021). "The relative risk of modifiable dementia risk factors varies widely between 1.1 for air pollution to 1.9 for hearing loss and depression and dramatically increases for genetic (APOE ɛ4 genotype) and biological (amyloid and tau deposition) risk factors." (PMID 34635163, 2021). "Compared to non-carriers, heterozygote (prevalence 25%) and homozygote (prevalence 2%) APOE ε4 carriers had increased risk of dementia, sub-distribution hazard ratios 2.19 (95% CI 1.73, 2.77) and 5.97 (95% CI 3.85, 9.28) respectively." (PMID 33397450, 2021). "The presence of executive function decline in VCI is also supported by findings from a prospective study examining changes to cerebral blood flow in healthy older adults with the APOE-ε4 allele dementia-risk-gene." (PMID 36324708, 2021). "TOMM40/APOE locus linked to dementia (p = 2.40 × 10−4) and arthritis (p = 3.01 × 10−3), and TMEM43 was associated with Parkinson's disease (p = 0.045)." (PMID 33657282, 2021). "Given the critical role of APOE in modulating cognitive function and dementia risk, we next tested if a mental stressor would reveal further genotype-specific differences in energy expenditure." (PMID 34488832, 2021). "In a prospective community-based cohort independent of the IGAP consortia, PRS positivity expressed significant predictive ability of AD diagnosis beyond APOE status, with stronger associations to AD than VD, MD, or all-cause dementia." (PMID 32404947, 2021). "Among Whites, the overall proportion developing dementia was 38% higher among those with at least one APOE ε4 allele (47.0% prevalence, 95% CI: 44.4, 49.6%, among carriers vs. 33.9% prevalence, 95% CI: 32.0, 35.7%, among non-carriers)." (PMID 34744974, 2021). "Here, we used prospective data from a large population-based study to examine the interaction between genetic predisposition including APOE genotype and polygenic risk and smoking in contributing to the risk of dementia." (PMID 34155245, 2021). "In this study, we demonstrated that PRS+APOE was significantly associated with an increased risk of progression to dementia in MCI." (PMID 34465370, 2021).
dementia (continued). "There is growing evidence that protection from dementia risk can be conferred by both common and rare genetic variants, especially in the high‐risk APOE ε4/ε4 group." (PMID 34041846, 2021). "Medication intake was significantly higher within cases than controls, as well as the prevalence of diabetes and cardiovascular diseases, and the presence of the APOE‐ε4 allele, which are well‐known risk factors for CD and dementia." (PMID 34661340, 2021). "Our findings are in keeping with those of studies on dementia being associated with prognosis in COVID-19; one such study reported how the presence of the ApoE e4e4 allele—the gene associated with dementia—puts a patient at risk for severe COVID-19." (PMID 34280188, 2021). "Several genes occupy central nodes in the protein network: APOE occupies a central node in the protein network and in our analysis is associated with the family history of dementia." (PMID 33935957, 2021). "In contrast, studies conducted at midlife found that moderate to high intake of saturated fats in relation to an increased risk of dementia/AD was only detected or more pronounced among APOE ε4 carriers." (PMID 33748832, 2021). "After stratifying by the AD‐PRSs tertiles, APOE ɛ4 carriership was only associated with incident dementia among those in the low‐ and middle‐risk tertiles." (PMID 33532541, 2021). "In conclusion, we found an effect of AD‐PRSs (including 39 SNPs or 57 SNPs) and APOE genotype on dementia risk in the general population up to very old ages, especially among APOE ɛ4 non‐carriers." (PMID 33532541, 2021). "Although case-control and longitudinal studies have examined the association of APOE with dementia, its association with cognitive decline over the adult life course remains debated." (PMID 33397450, 2021). "In a population‐based sample of individuals aged 70 to 111 years, AD‐PRSs (including 39 or 57 SNPs) were associated with incident dementia, particularly in APOE ɛ4 non‐carriers and in those aged 95 years or older." (PMID 33532541, 2021). "By leveraging a large multiracial population-based cohort with thorough outcome ascertainment and a long duration of follow-up, our findings support prior work showing both elevated risk and shorter time to dementia diagnosis by APOE ε4 allele carrier status." (PMID 34744974, 2021). "APOE‐4 homozygosity increased risk of severe COVID‐19 infection in dementia and non‐dementia participants." (PMID 34043836, 2021). "There is also an APOE-COVID-19 connection, based on the fact that APOE-ε4 is a risk for dementia and for delirium, and that in older adults, pre-existing dementia and delirium are risk factors for severity of COVID-19." (PMID 34205498, 2021). "Participants who developed dementia were older at baseline and were more likely to carry an APOE-ε4 allele." (PMID 34279450, 2021). "The patterns were associated with variables such as age, sex, APOE ε4 carrier status, BMI, cognitive activity, and were differently related to key outcomes such as dementia and death." (PMID 34232918, 2021). "Many of the analogs also revealed an enhanced ability to activate LXRE-mediated transcription, intimating their ability to significantly stimulate LXR/LXRE target genes such as ApoE, which have been implicated in protection against dementias." (PMID 34830251, 2021). "Although we also detected association between APOE ε4 and dementia status and cognitive performance, these were all mediated by tauopathy, highlighting that they are a consequence of the neuropathological changes." (PMID 33376986, 2020). "Here, we tested the impact of APOE-ε4 and two other risk factors, a family history of dementia and obesity, on grey matter macro- and microstructure across the whole brain in 165 asymptomatic individuals (38–71 years)." (PMID 33188215, 2020). "Our findings suggest that APOE ε4 can be used as a marker for the development of dementia in elderly CADASIL patients with less pathogenic NOTCH3 variants." (PMID 33328970, 2020).
dementia (continued). "Another gene of interest has been apolipoprotein E (APOE), due to the observation of pre-existing dementia as a risk factor for COVID-19 severity and mortality in the older UK Biobank population (age range ~ 40–69 years; UKBB)." (PMID 33414783, 2020). "Given the association between APOE ε4 and dementia risk, it raises the question as to the potential contribution of WMHs to this risk." (PMID 32971464, 2020). "What is the association of apolipoprotein E (apoE) protein levels in different lipoproteins with cognitive function and risk of dementia?" (PMID 32648923, 2020). "Rosuvastatin medication significantly alleviated the cognitive impairment progression and the risks of dementia in patients with APOE ε4 allele." (PMID 32581766, 2020). "In particular, ApoE ɛ4 allele has been demonstrated as one of the most important genetic risk factor for dementia in various population-based studies worldwide, and is notably associated with hippocampal atrophy." (PMID 32060376, 2020). "Patients with AD dementia were less educated and more frequently presented the ApoE ε4 allele compared to the controls; moreover, they had longer disease duration than patients with MCI." (PMID 32967721, 2020). "Recently, one study showed that low job control modified the association between APOE ɛ4 and dementia." (PMID 32081835, 2020). "Compared with subcohort members, more participants who subsequently developed dementia during follow-up had MCI and carried the APOE ε4 allele (dementia cases during follow-up: 197 of 521 participants [38%]; random subcohort: 154 of 995 participants [15.5%])." (PMID 32648923, 2020). "The findings of this study extend the beneficial associations of the novel apoE–positive, apoC3–negative lipoprotein from cardiovascular disease to dementia." (PMID 32648923, 2020). "The APOE ε4 allele was significantly associated with younger age of death in the Brains for Dementia Research cohort." (PMID 33376986, 2020). "In the subgroup analyses by dementia subtypes, the association of the ApoE gene with the risk of AD (OR = 3.62; 95% CI: 3.03–4.32; P < 0.01) was stronger across the comparison of ε4 vs. ε3." (PMID 32398686, 2020). "Appetite and agitation presented the highest incremental risk of conversion to dementia (> 85%) in the additive interactions with APOE ɛ4." (PMID 33208795, 2020). "An autopsy study of various dementias found that the APOE-ε4 allele frequency was significantly elevated in AD but was comparable to the control frequency in FTD." (PMID 33312717, 2020). "The effects of APOE ɛ4 (β = 0.232, 95% CI [− 0.002–0.466]) and age (β = 0.070, 95% CI [0.047–0.093]) on dementia were also positive, indicating risk increase." (PMID 32887574, 2020). "One research group has studied the association of ApoE genotypes on dementia in patients with latent toxoplasmosis." (PMID 32545619, 2020). "The ApoE e4e4 homozygous genotype was found to increase the risk of severe COVID-19, independently of pre-existing dementia, cardiovascular disease, and type 2 diabetes." (PMID 33092637, 2020). "According to our studies, the association between dementia and APOE-ε4 is weaker in Caribbean Hispanics compared to Caucasian populations." (PMID 33537283, 2020). "The new wave aim to determine the changes in prevalence and incidence of dementia in the region and its associated risk factors—emphasizing cardiovascular issues—and to evaluate probable associations with APOE gene, markers of inflamation and immunusenescence." (PMID 33537283, 2020). "Of the 87 patients, the presence of APOE ε4 genotype was associated with dementia at baseline examination (odds ratio 3.51; 95% CI 1.01–12.1; p = 0.021)." (PMID 33328970, 2020). "We observed the APOE-ε4 allele was longitudinally associated with higher risk of dementia, in a dose dependent manner." (PMID 33143703, 2020). "Apolipoprotein E ε4 genotype was associated with an increased risk of incident dementia [hazard ratio, 10.70 (1.27–89.88)]." (PMID 33328970, 2020).
dementia (continued). "In this MR meta-analysis, ApoE gene polymorphism was utilized as an instrumental variable to evaluate the potential causal relation between circulating cholesterol and the risk of dementia." (PMID 32398686, 2020). "This estimation is particularly relevant when observing that the incremental mean risk of conversion to dementia associated with APOE ε4 and NPS’ main effects are 44% and 14%, respectively." (PMID 33208795, 2020). "Dementia and COVID-19 share many co-morbidities and risk factors, including age, gender, hypertension, diabetes, obesity and possession of APOE ε4—most of which are associated with an overactive RAS, cerebrovascular dysfunction and neuroinflammation." (PMID 33380345, 2020). "As has been shown previously in this study cohort, the presence of at least one APOE ɛ4 allele was related to an increased risk of incident dementia." (PMID 32111184, 2020). "For example, low plasma ApoE levels are consistently linked to an increased risk of AD and dementia, whereas ApoE levels in the AD CNS have been described as up-regulated, down-regulated, or unchanged." (PMID 31978088, 2020). "In this case-cohort study including 1351 community-dwelling participants 74 years and older, the presence of apoE in high-density lipoproteins that lack apoC3 was associated with better cognitive function and decreased risk of dementia." (PMID 32648923, 2020). "Higher late‐life LIBRA scores were related to higher dementia risk among apolipoprotein E (APOE) ε4 non‐carriers." (PMID 31736136, 2020). "Although mutations of several proteins, including tau-protein, apolipoprotein E, presenilin have already been found in severe forms of dementias, for decades, amyloid plaques were considered one of the primary causes of AD." (PMID 32469963, 2020). "In conclusion, APOE ε4 genotype was associated with the development of incident dementia, and higher blood pressure was associated with significantly increased risk of incident stroke in CADASIL patients with predominant p.Arg544Cys mutation." (PMID 33328970, 2020). "Apolipoprotein (APOE) e4 genotype is an accepted risk factor for accelerated cognitive aging and dementia, though its neurostructural substrates are unclear." (PMID 30903549, 2020). "The most important finding of the current study is that APOE ε4 allele was an independent risk factor for developing incident dementia in CADASIL patients." (PMID 33328970, 2020). "Our findings demonstrate the APOE region should be removed prior to polygenic risk score development and treated as an independent factor in dementia analyses." (PMID 33143703, 2020). "In contrast, the presence of apoE in high-density lipoproteins that contain apoC3 was unrelated to cognitive function and risk of dementia." (PMID 32648923, 2020). "A factor whose association with dementia is well established is apolipoprotein E ε4 (APOE*ε4) allele." (PMID 33308366, 2020). "The second aim was to investigate potential differences between persons with high and low genetic risk for dementia (APOE ε4 carriers versus non‐carriers) regarding the relations of the LIBRA score with dementia and MCI risk." (PMID 31736136, 2020). "The precise biological mechanisms of how APOE-ε4 modifies the effects of obesity on the risk of late-life dementia are still poorly understood." (PMID 32575116, 2020). "Genetic variants of the adjacent TOMM40 and APOE on Ch19q13.3 are independently and additively associated with dementia risk in Caucasian and African-American populations." (PMID 32587511, 2020). "Significant interactions between late‐life LIBRA scores and APOE ε4 carrier status were found in relation to dementia risk (P = .011)." (PMID 31736136, 2020). "The ApoE e4 genotype is associated with both dementia and delirium, with the e4e4 (homozygous) genotype associated with a 14-fold increase in risk of Alzheimer’s disease compared to the common e3e3 genotype, in populations with European ancestries." (PMID 32451547, 2020).